ELOVL6 (ELOVL fatty acid elongase 6)
Diseases named in the same sentence as ELOVL6 in open-access papers (continued):
Sharing a sentence is not in itself a finding about the gene and the disease.
fibrosis (1 paper, 2018). the formation of excess fibrous connective tissue in an organ or tissue in a reparative or reactive process. "Furthermore, patients with advanced fibrosis had lower D5D activity (ratio of 20:4n-6/20:3n-6) and ELOVL6 activity (ratio of 18:0/16:0)." (PMID 30380656, 2018). "The analysis of enzymatic activities based on RBC FA composition revealed that both D5D activity (ratio of 20:4n-6/20:3n-6) and ELOVL6 activity (ratio of 18:0/16:0) were lower in patients with advanced fibrosis than in those without advanced fibrosis (p = 0.010; p = 0.014, respectively)." (PMID 30380656, 2018). "We observed that patients with advanced fibrosis did not present a higher intake of SFA compared to patients without advanced fibrosis, which suggests that the palmitic acid increase found in RBC reflects increased de novo lipogenesis (DNL), in addition to reduced ELOVL6 activity." (PMID 30380656, 2018).
gallstones (1 paper, 2015). Solid crystalline precipitates in the biliary tract, usually formed in the gallbladder, resulting in the condition of cholelithiasis.
germinoma (1 paper, 2010). A malignant germ cell tumor arising in the central nervous system. "Six genes (BANK1, CXCL9, CXCL11, DDIT4L, ELOVL6 and HERC5) within 4q13.3-4q28.3 were more abundant in germinomas." (PMID 20178649, 2010).
Glucose intolerance (1 paper, 2014). Glucose intolerance (GI) can be defined as dysglycemia that comprises both prediabetes and diabetes. "Elovl6−/− mice developed the same degree of glucose intolerance as wild-type mice after feeding the high-fat/high-sucrose diet." (PMID 25281760, 2014).
gout (1 paper, 2016). A condition characterized by painful swelling of the joints, which is caused by deposition of urate crystals. "The SNP rs12504538, located in the elongation of very-long-chain-fatty-acid-like family member 6 gene (Elovl6), was found to be associated with gout susceptibility (Padjusted = 0.00595)." (PMID 27506295, 2016).
lipid metabolism disorder (1 paper, 2024). "These DEGs included ACSL1, ANGPTL3, and ELOVL6, suggesting the possibility of a lipid metabolism disorder in the liver of exposed T. scripta elegans." (PMID 39088466, 2024).
liver fibrosis (1 paper, 2017). "While ELOVL6 expression had only little impact on hepatic lipid content, deficiency in ELOVL6 reduced ROS, liver fibrosis and activation of the inflammasome after PA treatment." (PMID 28877220, 2017). "Recently it was reported that ELOVL6 is involved in NASH related pathogenesis including oxidative stress, inflammatory damage and liver fibrosis." (PMID 28877220, 2017).
lung adenocarcinoma (1 paper, 2023). A carcinoma that arises from the lung and is characterized by the presence of malignant glandular epithelial cells. "The aim of this paper was to reveal the correlation between the expression of ELOVL fatty acid elongase 6 (ELOVL6) gene in lung adenocarcinoma (LUAD) and its clinical significance, immune cell infiltration level and prognosis." (PMID 37682172, 2023).
melanoma (1 paper, 2025). A malignant, usually aggressive tumor composed of atypical, neoplastic melanocytes. "The downregulation of GPD1 and ELOVL6 further highlighted LA’s suppressive impact on melanoma metabolic pathways critical for tumor progression and survival." (PMID 39795195, 2025).
migraine (1 paper, 2017). "The most significant finding from the replication study was the association between ELOVL6 and migraine, a nuclear encoded gene which is transported into the mitochondrial matrix and plays a key role in energy metabolism." (PMID 28361102, 2017). "The replication study supported significant association with the genes ELOVL6 (P = 0.00035), SARDH (P = 0.00081), and CSNK1G3 (P = 0.00037) and migraine." (PMID 28361102, 2017). "After applying a Bonferroni correction, three SNPs located in ELOVL6, SARDH and CSNK1G3 pass the significance threshold suggesting a particularly important role for these genes in migraine susceptibility." (PMID 28361102, 2017).
neuroblastoma (1 paper, 2020). Neuroblastoma (NB) is the most common solid, extracranial childhood tumor. "Interestingly, six genes ARMC6, DCTPP1, EIF4G1, ELOVL6, FBL and PRMT1 were associated with the clinical overall survival of neuroblastoma in both TARGET and GSE85047 datasets." (PMID 32593299, 2020). "The present study suggested new prognostic markers of ARMC6, DCTPP1, EIF4G1, ELOVL6 and FBL in neuroblastoma and highlighted the combinational prognostic significance of MYCN amplification and EIF4G1 expression in patients with neuroblastoma." (PMID 32593299, 2020). "Therefore, functions and prognosis of ARMC6, DCTPP1, EIF4G1, ELOVL6 and FBL in neuroblastoma should be further studied." (PMID 32593299, 2020). "However, the functions and prognosis of ARMC6, DCTPP1, EIF4G1, ELOVL6 and FBL in neuroblastoma were not reported." (PMID 32593299, 2020).
oral squamous cell carcinoma (1 paper, 2023). "Then, ELOVL6 expression was validated in oral squamous cell carcinoma (OSCC), which is a common type of HNSCC, by immunohistochemical analysis." (PMID 36818393, 2023). "Finally, we validated ELOVL6 expression and its prognostic value in oral squamous cell carcinoma (OSCC), which is a common type of HNSCC." (PMID 36818393, 2023).
phospholipidosis (1 paper, 2012). "However, it is clear that our model predicts that the induction of phospholipidosis via the mechanism 3 targets ELOVL6 or SCD is unlikely, as neither is predicted to interact with any of the 100 positive phospholipidosis-inducing compounds." (PMID 22281160, 2012).
polyp (1 paper, 2022). A usually exophytic mass attached to the underlying tissue by a broad base or a thin stalk. "A significant difference in the expression of ELOVL6 and ATP2A3 was observed in tissues of patients with polyp and patients with COAD (P< 0.001 and P< 0.05, respectively)." (PMID 36532007, 2022).
retinal degeneration (1 paper, 2018). Degeneration of the retina. "In this study we show that loss of Baldspot/ELOVL6 activity can affect the outcome of retinal degeneration and has the potential to be a broader regulator of ER stress-associated diseases." (PMID 30081392, 2018).
retinitis pigmentosa (1 paper, 2018). Retinitis pigmentosa (RP) is an inherited retinal dystrophy leading to progressive loss of the photoreceptors and retinal pigment epithelium and resulting in blindness usually after several decades. "Our findings suggest that ELOVL6 is a promising target in the treatment of not only retinitis pigmentosa, but a number of different ER stress-related disorders." (PMID 30081392, 2018).
squamous cell carcinoma (1 paper, 2017). A carcinoma arising from squamous epithelial cells. "In squamous cell carcinoma of lung, excessive expression of ELOVL6 was observed, and it was suggested that ELOVL6 inhibition might result in antitumor activity." (PMID 28851309, 2017).
cancer (20 papers, 2012 to 2026). A tumor composed of atypical neoplastic, often pleomorphic cells that invade other tissues. "Our finding that Elovl6 loss hampers AML propagation will facilitate the development of novel cancer treatments; ELOVL6 activity or pathways regulated by ELOVL6 are potential targets of anti-AML therapy." (PMID 36890291, 2023). "This tightly regulated and transient activation of ELOVL6 may represent an adaptive mechanism to acute lipid-derived stress, the dysregulation of which could contribute to metabolic disorders and cancer-associated lipid remodeling." (PMID 41768220, 2026). "Taken together, these data suggest that high expression of Elovl6 may be associated with cancer progression." (PMID 29700319, 2018). "The differential expression of ELOVL6 in 57 paired cancer tissues versus paraneoplastic tissues from the TCGA database was analyzed, and the results revealed that ELOVL6 expression was significantly lower in paraneoplastic tissues than in cancer tissues." (PMID 37682172, 2023). "Here, Elovl6 is essential in cancer cell proliferation; a higher ELOVL6 expression accompanies greater tumor growth, and thus, a greater aggressiveness of this cancer." (PMID 36291290, 2022). "Elevated expression of genes such as ABCC5, LRFN1, ELOVL6, and HTR2B have been associated with metastasis in other cancer types." (PMID 34680307, 2021). "A functional screen followed by phospholipidomic analysis revealed that ELOVL6 is mainly responsible for phospholipid acyl chain elongation in cancer cells." (PMID 28273089, 2017). "Functional screening of differentially expressed ELOVLs by selective gene knockdown in SCC cell lines followed by phospholipidomics revealed ELOVL6 as the main elongation enzyme responsible for acyl chain elongation in cancer cells." (PMID 26862848, 2016). "The use of the siRNAs for ELOVL4 and ELOVL6 reduced cancer cell proliferation and migration rates." (PMID 38139442, 2023). "Moreover, high ELOVL6 expression correlates with poor prognosis of patients with breast and liver cancer." (PMID 36890291, 2023). "Expression profile data of ELOVL6 mRNA were collected from the cancer genome atlas database to analyze the differences in ELOVL6 mRNA expression in LUAD tissues and normal lung tissues, and to analyze the correlation between ELOVL6 and information on clinicopathological features." (PMID 37682172, 2023). "To investigate whether the regulation of Elovl6 and Scd1 gene expression by Rb is applicable to human cancer patients, we analyzed cBioPortal database." (PMID 28650445, 2017). "Importantly, our findings indicate that reversal of the elongation phenotype by inhibition of ELOVL6 affects cancer biology and may have potential for antineoplastic intervention." (PMID 26862848, 2016). "As Compound A is not highly optimized for use in vivo, this study suggests that ELOVL6 has significant potential as target for cancer intervention and sparks the interest in finding better chemical inhibitors with improved in vivo efficacy that could reverse the elongation phenotype in tumor tissue." (PMID 26862848, 2016). "PPAR signaling pathway has been previously reported to be regulated by NAT10 through ac4C modification of genes such as ELOVL6, ACSL1, ACSL3, ACSL4, ACADSB, and ACAT1, thus modulating fatty acid metabolism in cancer cells." (PMID 40123006, 2025). "However, the role of Elovl6 in cancer progression remains unknown." (PMID 29700319, 2018). "Thus, inhibition of Elovl6 may be a potential strategy for cancer treatment." (PMID 29700319, 2018). "Met downregulated expression of enzymes of fatty acid de novo synthesis, such as ATP Citrate Lyase (ACLY), Fatty Acid Synthase (FAS), Fatty Acyl-CoA Elongase 6 (ELOVL6), and Stearoyl-CoA Desaturase-1 (SCD1) in cancer cells." (PMID 28230778, 2017). "Similarly, ELOVL6 and ELOVL7 have been reported to be overexpressed in various tumors and contribute to cancer progression." (PMID 40552308, 2025).
cancer (continued). "As ELOVL6 has a strong substrate specificity for C16:0 and C16:1, which it converts to C18:0 and C18:1, respectively, we analyzed the differences in acyl chain composition of phospholipids in cancer versus non-malignant tissue in more detail by tandem MS." (PMID 26862848, 2016). "To confirm that ELOVL6 expression is mainly confined to the cancer cells in clinical SCC tissue, we used RNAscope as no specific antibodies against ELOVL6 are available and also the generation of own antibodies failed." (PMID 26862848, 2016).
tumor (20 papers, 2016 to 2025). "In the present study, we found that knockdown of Elovl6 expression caused cell cycle arrest and inhibited tumor cell proliferation through the inhibition of the Akt-mediated signaling pathway." (PMID 29700319, 2018). "Depletion of Elovl6 or Scd1 significantly suppressed colony formation, sphere formation and xenograft tumor growth of Rb-deficient tumor cells." (PMID 28650445, 2017). "After treatment with tumor cell-conditioned medium, 3T3-L1 mouse preadipocytes showed a decrease in Elovl6 expression, and Elovl6-knockdown cells exhibited a reduction in preadipocyte differentiation and lipogenesis." (PMID 38760797, 2024). "Based on TIMER database, TISDIB database and GEPIA2 database, the correlation between ELOVL6 expression and tumor immune cell infiltration in LUAD was analyzed." (PMID 37682172, 2023). "Univariate and multifactorial analyses showed that tumor TNM stage was associated with prognosis of LUAD patients, and ELOVL6 expression was an independent factor for prognosis of LUAD patients." (PMID 37682172, 2023). "The expression of ELOVL6 in the women was lower (p = 0.03) in the tumor core than in the peritumoral area, and was lower than in the men (p = 0.04)." (PMID 36291290, 2022). "Previous works have also reported that ELOVL6 is a target gene of miR-22, and is also involved in the fatty acid synthesis and the elongation of liver cells and tumor cells." (PMID 36077994, 2022). "In the men, the expression of the elongases positively correlated with BMI —in particular, the ELOVL2 expression in the peritumoral area and tumor core, and ELOVL5 and ELOVL6 expressions in the enhancing tumor region." (PMID 36291290, 2022). "We showed that the expression of ELOVL2, ELOVL5, and ELOVL6 in the GBM tumor was lower in women than in men." (PMID 36291290, 2022). "HPV+ patients with tumours expressing low levels of ELOVL6 had significantly better five-year overall survival than patients with tumours expressing high levels of ELOVL6 (p = 0.0040, q = 0.084)." (PMID 31968678, 2020). "In contrast genes involved in development and differentiation (Arid5b, Inmt, Grem2, Gdap10), cell metabolism (Alas1, Gsta1, Thrsp, Fdft1, Elovl6), tumor growth (SerpinA4, Cish, Rpl36), and cell cycle control (PLK3, Myc, HNF6/Onecut1) were downregulated." (PMID 33004985, 2020). "Consistent with our analysis findings, the mean expression levels of SLC43A1 and ELOVL6 were significantly lower while HOXC8 was significantly higher in CCA samples than in non-tumor liver samples in the GSE26566 dataset." (PMID 31448221, 2019). "In the present study, 30 pairs of HCC sample and non-tumor liver tissues were analyzed for mRNA expression of Elovl6." (PMID 29700319, 2018). "In the present study, we investigated the effect of Elovl6 on tumor growth in vitro and in vivo and analyzed the correlation between Elovl6 and clinical features to better understand the role of Elovl6 in HCC." (PMID 29700319, 2018). "Collectively, knockdown of Elovl6 expression in HCC suppresses tumor growth and enhances survival in mice bearing syngeneic HCC." (PMID 29700319, 2018). "Our results show that high expression of Elovl6 in HCC is correlated with higher incidence of recurrence after tumor resection and poorer overall survival in patients with HCC." (PMID 29700319, 2018). "In the current study we show that chemical inhibition of ELOVL6 by Compound A interferes with tumor growth in vivo in two independent models." (PMID 26862848, 2016). "Meanwhile, there was a statistically significant correlation between ELOVL6 expression abundance and tumor immune infiltration level, which may provide new ideas for LUAD treatment." (PMID 37682172, 2023). "Furthermore, SLC27A3 expression was positively correlated with ELOVL6 expression in the enhancing tumor region and tumor core." (PMID 37239243, 2023). "Additionally, the ELOVL5 expression in the tumor core was positively correlated with the ELOVL6 expression in the enhancing tumor region." (PMID 36291290, 2022).
tumor (continued). "Additionally, there was a positive correlation in the ELOVL2 expression in the tumor core with the ELOVL6 expression in the enhancing tumor region." (PMID 36291290, 2022). "The expression of CD36, PTGR1, SUCLG2, CPT2 and ELOVL6 were downregulated in tumor tissues." (PMID 36568396, 2022). "Inhibition of Elovl6 reduced tumor growth and prolonged survival in mice bearing tumors." (PMID 29700319, 2018). "Given that Elovl6 expression caused lipid accumulation and resulted in reduced cell growth, we further investigated whether suppression of Elovl6 expression inhibited tumor growth in vivo." (PMID 29700319, 2018). "Simultaneously, inhibition of Elovl6 led to increased Cx32 expression in the tumor samples." (PMID 29700319, 2018). "Moreover, in line with the substrate specificity of ELOVL6 for C16:0 and C16:1, we discovered that tumor tissue contained phospholipid species with a higher content of C18:0 and C18:1 at the expense of C16:0 and C16:1 compared to normal tissue." (PMID 26862848, 2016). "Moreover, also local chemical inhibition of ELOVL6, via intra-tumoral injection of Compound A, significantly attenuated tumor formation by KLN205 SCC cells grown as subcutaneous xenografts in syngeneic DBA/2 mice." (PMID 26862848, 2016). "The ELOVL3 expression in the tumor core was negatively correlated with ELOVL5 and ELOVL6 expressions in the enhancing tumor region." (PMID 36291290, 2022). "The same correlation was also found in men, i.e., BMI vs. ELOVL5 and ELOVL6 expressions in the enhancing tumor region and the ELOVL2 expression in the tumor core." (PMID 36291290, 2022). "This study examines the expression of elongases ELOVL1, ELOVL2, ELOVL3, ELOVL4, ELOVL5, ELOVL6, and ELOVL7 in GBM tumor samples from 28 patients (16 men and 12 women), using a quantitative real-time polymerase chain reaction (qRT-PCR)." (PMID 36291290, 2022). "There was a positive correlation between ELOVL4, ELOVL5, ELOVL6, and ELOVL7 expressions in the GBM tumor." (PMID 36291290, 2022). "We show that suppression of Elovl6 inhibits HCC cell proliferation in vitro and tumor growth in vivo." (PMID 29700319, 2018). "Conversely, the expression of protective types (ACOX1, CPT2, ELOVL6, SUCLG2) was reduced in the H-R cohort than in the L-R cohort, implying that the eight-gene model accurately predicted prognosis and their possible effect on tumor incidence and growth." (PMID 38186579, 2023). "In the women, there was a negative correlation between ELOVL5 and ELOVL6 expressions in the GBM tumor and BMI." (PMID 36291290, 2022). "Additionally, the ELOVL1 expression in the tumor core was positively correlated with ELOVL4, ELOVL5, ELOVL6, and ELOVL7 expressions." (PMID 36291290, 2022). "Whereas two control tumors grew progressively, Elovl6 knockdown tumors were diminished 10 days after tumor cell inoculation and did not recur during the 50-day observation period." (PMID 29700319, 2018). "Moreover, depletion of either Elovl6 or Scd1 in RN6 cells resulted in significant attenuation of colony formation and tumor initiation in immune-compromised mice." (PMID 28650445, 2017). "ELOVL6 expression was indeed found mainly in tumor cells, whereas in normal lung cells, almost no ELOVL6 expression was observed." (PMID 26862848, 2016). "Here we show that inhibition of ELOVL6 affects colony formation in soft agar, and tumor growth in vivo but not in monolayer, suggesting that mechanisms of anchorage-independent growth are affected by ELOVL6-mediated acyl chain elongation." (PMID 26862848, 2016).